WT1 (WT1 transcription factor)
Diseases named in the same sentence as WT1 in open-access papers (continued):
Sharing a sentence is not in itself a finding about the gene and the disease.
Wilms tumor (continued). "We present a case of a patient with Wilms tumor, nephropathy, hermaphroditism, and a novel mutation in the WT1 gene." (PMID 33942367, 2021). "The Wilms’ tumor 1 (WT1) gene was originally identified based on its mutational inactivation in Wilms’ tumor (nephroblastoma)." (PMID 34299295, 2021). "The WT1 gene is a transcription factor essential for normal development of the urogenital system and encodes for Wilms tumor protein located on chromosome 11p13." (PMID 34943491, 2021). "Both CTNNB1 and WT1 mutations have been previously implicated with Wilms’ tumor genesis, and both clone types were present in every profiled region." (PMID 32843649, 2020). "One subgroup of Wilms tumors is associated with mutations in the WT1 gene, encoding a transcription factor with a role in early kidney differentiation." (PMID 33379206, 2020). "We developed a new method to reproducibly establish long-term cultures of Wilms tumors with WT1 mutations." (PMID 33379206, 2020). "The major gene of predisposition to Wilms Tumor (WT1) was, however, ranked 483rd, as its expression was high in both WT and AML samples." (PMID 31988326, 2020). "The human Wilms’ tumor (WT1), the gene encoding the zinc finger transcription factor, is important for cell survival, differentiation, and proliferation." (PMID 32178481, 2020). "Third, detection of certain mutations allows prediction and further screening of renal and extrarenal comorbidities and helps to avoid possible future complications, e.g., risk of Wilms’ tumor or gonadoblastoma in patients with WT1 mutations." (PMID 32604935, 2020). "WT1 was first identified as a candidate tumor susceptibility gene for Wilms' tumor, the most common pediatric renal malignancy." (PMID 33110919, 2020). "Although WT1 was first identified as a tumor susceptibility gene in Wilms' tumor, overexpression of the WT1 gene in other types of malignancy suggested its oncogenic role." (PMID 33110919, 2020). "We developed a method to cultivate cells from the WT1 mutant subtype of Wilms tumors and have established 11 cell lines with different mutations in WT1 to date." (PMID 33379206, 2020). "We have shown previously that WT1 mutant Wilms tumors display great heterogeneity of second CTNNB1 mutations in vivo." (PMID 33379206, 2020). "WT1 gene mutations are linked with a subset of Wilm’s tumors, the most common pediatric renal cancer." (PMID 31795964, 2019). "Our study identified TRIM28 as a major Wilms tumour predisposition gene, making a similar contribution to familial and unselected Wilms tumour as those of constitutional WT1 and REST mutations." (PMID 30885698, 2019). "Haploinsufficiency of WT1 is associated with Wilms tumor, while dysregulated WT1 expression is associated with tumors including leukemia, testicular germ cell tumors and uterine leiomyosarcoma." (PMID 31249589, 2019). "Wilms’ tumor gene (WT1) encodes a transcription factor, which was originally identified as mutated in patients with Wilms’ tumor, a nephroblastoma that typically occurs in children." (PMID 30897713, 2019). "Following detailed mapping of this chromosome region, the causative genes for Wilms tumour and genitourinary anomalies (WT1) and classical aniridia (PAX6) were found to lie within a megabase of each other." (PMID 30242502, 2019). "Germline inactivation of the Wilms Tumor 1 (WT1) transcription factor has been linked to a genetic predisposition towards Wilms tumor." (PMID 31616462, 2019). "An example is the WT1 mutation, which can predispose to malignancy, and the detection of such mutations should trigger monitoring for associated Wilms’ tumour and gonadoblastoma." (PMID 29181713, 2019). "First, the discovery of inactivating mutations and deletions of WT1 in Wilms tumours led to the revelation of its key roles in development of numerous embryonic tissues." (PMID 29912901, 2018).
Wilms tumor (continued). "Around 10% of sporadic Wilms' tumor specimens have inactivating mutations in WT1, and these same tumors often also contain mutations in β-catenin (CTNNB1)." (PMID 30459215, 2018). "Approximately 5–20% of Wilms' Tumors cases exhibit somatic WT1 gene mutations which tend to be sporadic bi-allelic aberrations occurring in blastemal progenitors." (PMID 29623275, 2018). "Here, we show that a longer preoperative chemotherapy of WT1‐mutant Wilms tumor patients can be associated with the development of terminally differentiated skeletal muscle cells, which are unable to proliferate in vitro in two patients." (PMID 29542868, 2018). "Mutations in WT1, Cited1, and Six2 result in Wilms' Tumors when they occur in pluripotent nephrogenic progenitors but not in stromal progenitors." (PMID 29623275, 2018). "This potential novel molecular mechanism for the induction of terminal muscle cell differentiation with concomitant loss of malignant growth potential of WT1‐mutant Wilms tumor cells will require final functional confirmation." (PMID 29542868, 2018). "WT1 was known as a tumor repressor gene causatively involved in eponymous nephroblastoma, but was recently revealed as a transcription factor with strong transactivating potential in organogenesis." (PMID 30103817, 2018). "The inherited nature of mono-allelic germline WT1 mutations or deletions occurring within chromosomal regions 11p13 predisposes individuals to Wilms' Tumor formation and account for ~5% of WT cases." (PMID 29623275, 2018). "Inactivating mutations occurring in WT1 during embryonic kidney development result in the formation of the pediatric renal neoplasm Wilms' tumor (WT)." (PMID 29623275, 2018). "The genetic aberrations underlying this process are varied and include inactivating mutations of Wilms tumor 1 (WT1), Wilms tumor gene found on chromosome X (WTX), and stabilizing/activating mutations of β‐catenin (CTNNB1)." (PMID 28188683, 2017). "The Wilms’ tumour 1 (WT1) gene, located at chromosome 11p13, encodes a zinc transcription factor firstly identified as a tumour suppressor gene in nephroblastoma or Wilms’ tumour, a pediatric kidney cancer." (PMID 28107196, 2017). "We have previously established a number of cell lines that were derived from Wilms tumors with WT1 mutations." (PMID 27213811, 2016). "By microdissection of tumor material and ILNR lesions it has been observed that various different CTNNB1 mutations occur in WT1 mutant cells, an example of genetic heterogeneity in Wilms tumor (unpublished observation Uschkereit and BR-P)." (PMID 27213811, 2016). "Genetic analyses of cells derived from the Wilms tumor (Wilms10) showed the same WT1/11p13 alteration but a different mutation in CTNNB1 as compared to the bulk tumor DNA." (PMID 27213811, 2016). "In these Wilms tumors three “hits” occurred; the first is a germ line WT1 mutation, the second is the loss of heterozygosity (LOH) in 11p, resulting in loss of the WT1 wild type allele and the third is a CTNNB1 mutation." (PMID 27213811, 2016). "Abnormalities in WT1 gene, have been associated with the pathogenesis of Wilms tumor, Denys-Drash syndrome, and Frasier syndrome." (PMID 27014421, 2016). "All established Wilms tumor derived cell lines from tumors with WT1 mutations as well as Wilms10 cells have a limited in vitro growth potential." (PMID 27213811, 2016). "Most cell lines that we have established from WT1 mutant Wilms tumors have additional CTNNB1 mutations and the WT1 mutation is either homozygous due to a mitotic recombination event or the cells have a deletion on one allele and a mutation in the other allele." (PMID 27213811, 2016). "Wilms tumor 1 gene (WT1) was firstly identified as a tumor suppressor gene, encoding a 49–52 kDa protein with four zinc fingers in C-terminal domain in nephroblastoma, also known as Wilms tumor, a childhood tumor of the kidney." (PMID 27821145, 2016).
Wilms tumor (continued). "Earlier cytogenetic studies of patients with WAGR (MIM#194072), a syndrome characterized among others by susceptibility to Wilms tumor, revealed constitutional deletions on chromosome 11p13 affecting several contiguous genes including WT1." (PMID 26913079, 2016). "These contributions are relevant considering previous reports, where WT-1 and Hsp70 are physically associated (localized) in embryonic rat kidney cells, in primary Wilms’ tumor samples, and in cultured cells with inducible WT-1 expression." (PMID 27009470, 2016). "WT-1 and Hsp70 are physically associated in rat kidney cells, in primary Wilms’ tumor samples and in cultured cells with inducible expression of WT-1." (PMID 27009470, 2016). "The genetically best-defined subgroup of Wilms' tumours is the group caused by biallelic loss of the WT1 tumour suppressor gene." (PMID 26035382, 2015). "For example, patients with deletions encompassing WT1 have a high risk of Wilms tumor and renal failure." (PMID 26542297, 2015). "The Wilms’ tumors gene WT1 encodes an essential transcription factor, which functions in mammalian urogenital development." (PMID 26358501, 2015). "Although different groups of Wilms' tumours have been described, the genetically best-defined group still remains the 15-20% of cases that are caused by biallelic loss of the WT1 tumour suppressor gene." (PMID 26035382, 2015). "WT1 imprinting has been implicated in renal development and disease, as well as in the development of Wilms’ tumor." (PMID 25794157, 2015). "This led to the identification of the WT1 tumour suppressor gene, loss of which is the rate-limiting step in 15% of Wilms' tumours." (PMID 26035382, 2015). "WT1 encodes a zinc-finger transcription factor and was first described as a tumor suppressor gene in the pediatric kidney cancer, Wilms’ tumor." (PMID 26462627, 2015). "Wilms Tumor 1 (WT1) mutations and variants are implicated in several diseases, including Wilms tumor and acute myeloid leukemia (AML)." (PMID 25807502, 2015). "Wilms’ tumor gene 1 (WT1), which maps to human chromosome 11p13, encodes a zinc-finger transcription factor, firstly identified as a tumor suppressor gene in nephroblastoma or Wilms’ tumor, a pediatric kidney cancer." (PMID 25474318, 2014). "Denys-Drash syndrome includes mesangial sclerosis of the kidney and Wilms tumor caused by WT1 germline mutations." (PMID 24731683, 2014). "The Wilms’ tumor gene (WT1) located at chromosome 11p13 was originally identified as a tumor-suppressor gene associated with Wilms’ tumor, a kidney neoplasm of childhood." (PMID 25026998, 2014). "WT1 plays an important role in normal development of the urogenital system, and is named after its association with Wilms’ tumor development." (PMID 23890537, 2013). "WT1 germline mutation is known to result in a predisposition to Wilms tumors, male sex differentiation disorder, and early-onset renal failure." (PMID 23935527, 2013). "Sequencing analysis demonstrated that WT1 mutations were shown in only 10% of sporadic Wilms’ tumours." (PMID 23484026, 2013). "Mutation of the WT1 gene is implicated in Wilm's tumours; however, in this case we found cytoplasmic staining with nucleus sparing." (PMID 23150839, 2012). "Approximately 5% of such children have underlying constitutional mutations at WT1 or epigenetic defects at chromosome 11p15 that predispose to Wilms tumor." (PMID 22470196, 2012). "This is significantly lower than the other groups, and the median age of sporadic Wilms tumor (38 months) and is similar to tumors in children with constitutional WT1 mutations." (PMID 22470196, 2012).
Wilms tumor (continued). "We and others have shown that the 15–20% subset of Wilms' tumours arising through WT1 loss are more likely to be stromal (mesenchymal) predominant and often contain ectopic tissues, including bone, fat, cartilage and muscle." (PMID 22216009, 2011). "The WT1 gene was isolated as the gene responsible for a childhood renal neoplasm, Wilms' tumor, which is thought to arise due to the inactivation of both alleles of the WT1 gene located at chromosome 11p13." (PMID 21980425, 2011). "The Wilms' tumor suppressor protein WT1 plays a central role in the development of several organs and is mutated or aberrantly expressed in pediatric nephroblastoma." (PMID 20122399, 2010). "The syndrome is caused by haploinsufficiency for the PAX6 gene (causing aniridia) and the WT1 gene (predisposing Wilms' tumor, genital abnormalities and nephropathies)." (PMID 19222835, 2009). "The Wilms tumor suppressor gene WT1 encodes a Kruppel-like transcription factor which is mutated in a subset of Wilms tumor, a childhood kidney cancer." (PMID 18523561, 2008). "Chromosomal regions known to be associated with progression of Wilms' tumor are significantly enriched for the predicted targets of WT1." (PMID 18564415, 2008). "Chromosomal regions previously implicated in Wilms' tumor by cytological evidence are statistically enriched in predicted WT1 targets." (PMID 18564415, 2008). "DDS is caused by exonic point mutations in the WT1 gene, and is characterized by mesangial sclerosis with early kidney failure, high risk of Wilms' tumor, and varying degrees of gonadal dysgenesis associated with insufficient AMH production." (PMID 18445271, 2008). "The Wilms' tumor 1 suppressor gene (WT1) was first identified as a mutated gene in some cases of sporadic Wilms' tumor, a malignancy of the kidney affecting pluripotent embryonic renal precursor cells." (PMID 17634147, 2007). "As the gene is occasionally mutated in the sporadic form of Wilms' tumor, it was assumed that WT1 was a tumor suppressor and that the mutations abrogated that function." (PMID 17634147, 2007). "The Wilms tumour 1 (WT1) gene, isolated from the WT1 locus, was the first causative gene for Wilms' tumour." (PMID 16909133, 2006). "Mutations in the WT1 gene has been shown in a small proportion of nephroblastomas, an embryonic kidney tumor, as well as in other tumor types, such as leukemia, mesothelioma and desmoplastic small round cell tumor." (PMID 15613247, 2004). "Three loci have been implicated in familial Wilms tumour: WT1 located on chromosome 11p13, FWT1 on 17q12-q21, and FWT2 on 19q13." (PMID 10901367, 2000). "Wilms' tumor is a renal neoplasia commonly occurring in children and is associated with mutations of the WT1 gene." (PMID 10772697, 2000). "One of our patients with WT1 gene mutation had bilateral Wilms’ tumors." (PMID 39936125, 2025). "Mutations in the WT1 gene are associated with life-threatening nephropathy, GD, and Wilms’ tumor." (PMID 39936125, 2025). "We reported that 36% (47/129 cases) of patients with exon 8–9 WT1 variants had Wilms tumor." (PMID 39002031, 2025). "It is known that Wilms tumor/genitourinary malformations and aniridia are caused by deletions of the WT1 and PAX6 genes, respectively, but the causes of intellectual disability and autistic symptoms remain unclear." (PMID 40380139, 2025). "The Wilms’ tumor suppressor WT1 was first identified as a tumor suppressor due to its inactivating mutations in Wilms’ tumor (WT) or nephroblastoma, which is the most common pediatric renal cancer, caused by both excessive cellular proliferation and defective differentiation." (PMID 39768169, 2024).
Wilms tumor (continued). ",3,7, 8, 9, 10 Knowledge regarding risk for specific WT1-associated phenotypes, especially kidney disease, may have relevant clinical implications during and after treatment for Wilms tumor in childhood." (PMID 39698353, 2024). "Wilms tumors are among the most well-known clinical manifestations of WT1 variants." (PMID 39698353, 2024). "Many WT1 variants that are identified in patients with Wilms tumor only are truncating variants located outside the hotspot region, in contrast to the variants that were identified earlier in patients with Denys-Drash syndrome or severe, early-onset glomerulopathy." (PMID 39698353, 2024). "However, it remains challenging to compare the incidence rates of WT1 mutations in Wilms tumors across different races due to WT1-mutated sporadic or unilateral Wilms tumors having a considerably low incidence of less than 10%." (PMID 39272909, 2024). "Moreover, genetic diagnosis is useful for predicting kidney prognosis and detecting extrarenal complications properly and earlier such as gonadoblastoma and Wilms tumor in patients with WT1 gene variants." (PMID 38877226, 2024). "Approximately 20% of sporadic nephroblastomas exhibit WT1 gene mutations." (PMID 37999735, 2024). "CTNNB1 clonal mutations in Wilms tumor are diverted by WT1 mutations." (PMID 38929279, 2024). "However, it is now becoming clear that Wilms tumor development can be the initial presentation of a germline WT1 variant." (PMID 39698353, 2024). "However, it is now known that only about 5% of nephroblastoma incidence is caused by mutations in WT1; and most Wilms’ tumors exhibit high levels of WT1, which is also the case for most solid cancers as well as leukemia." (PMID 39768169, 2024). "Denys-Drash syndrome is linked to a germline WT1 gene mutation, with a 90% risk of nephroblastoma." (PMID 37999735, 2024). "Deletions in WT1 put patients at risk of developing nephroblastoma or Wilms tumors." (PMID 37542296, 2023). "With the increasing accessibility of human DNA sequencing and genomic screening, it will be possible to detect germline changes in the WT1 gene associated with an increased risk of developing Wilms tumor, as recommended by The American College of Medical Genetics and Genomics." (PMID 37568662, 2023). "In up to 15% of nephroblastoma cases, commonly known as the Wilms tumor (WT), malignant development is associated with germline mutations in cancer risk genes, such as single nucleotide variants or deletion of the WT1 gene, and some cancer predisposition syndromes." (PMID 37568662, 2023). "The Gessler group have previously treated primary Wilms tumour cells from two different patients; one tumour had predominantly stromal histology and a WT1 mutation, whereas the other tumour consisted of primary cells from a triphasic tumour without WT1 mutation." (PMID 37186071, 2023). "For example, understanding whether patients have a WT1 pathogenic variant associated with aniridia can help with Wilms tumor screening and treatment." (PMID 36981008, 2023). "Any early-onset Wilm's tumor or bilateral Wilm's tumor should have WT1 mutation analysis." (PMID 35498778, 2022). "However, in other Wilms’ tumors, wt1 is expressed at higher levels than normal, suggesting that only a small fraction of Wilms’ tumors are caused by loss-of-function of wt1." (PMID 36412640, 2022). "A recent single center retrospective analysis of 25 long-term Wilm's tumor survivors with WT1 pathogenic variants confirmed male predominance (60%), early age occurrence (median 14 months), multiple genetic variants, high incidence of bilateral disease (52%), and genitourinary malformations (44%)." (PMID 35498778, 2022). "The increased risk for Wilms tumor in patients with WAGR syndrome is caused by a haploinsufficiency of WT1 (OMIM: 607102); it has been suggested that LMO2 gene haploinsufficiency contributes to a further increase in this risk, based on a genotype–phenotype correlation analysis." (PMID 36011342, 2022).